TP63 (tumor protein p63)
Diseases named in the same sentence as TP63 in open-access papers (continued):
Sharing a sentence is not in itself a finding about the gene and the disease.
tumor (continued). "Together, our data indicate that TP63γ is the primary isoform of TP63 for tumor suppression but not development by maintaining normal inflammatory response and lipid homeostasis." (PMID 39915463, 2025). "Together, our data indicate that TP63γ is the primary isoform of TP63 for tumor suppression but not development by maintaining normal inflammatory response and lipid homeostasis, which can be explored as a therapeutic strategy to kill p63γ-deficient tumors." (PMID 39915463, 2025). "Furthermore, binding motifs for the OC stem and platinum tolerant tumour cell marker TP6325 are substantially enriched, suggesting ongoing activity within TP63-driven gene programs." (PMID 39341888, 2024). "Through assay for transposase-accessible chromatin using sequencing (ATAC-seq), we detected increased chromatin openness of squamous markers (TP63, KRT5, KRT6A and KRT14) and reduced chromatin accessibility of adenomatous markers (KRT7 and MLPH) in the DR tumor cells." (PMID 39687207, 2024). "Finally, we report a reciprocal inhibition between TP63 and STAT1 at the transcription level, which determines anti-tumor immune response of SCC cells by regulating the IFNγ signaling." (PMID 38509096, 2024). "To mimic IFN conditions in the tumor microenvironment (TME), we added IFNγ exogenously in SCC cells since (i) IFNγ pathway is the most significant pathway negatively regulated by TP63, (ii) IFNγ receptors (IFNGR1, IFNGR2) have higher expression than IFNα receptors (IFNAR1, IFNAR2) in SCC cells." (PMID 38509096, 2024). "Thus, only in the group of nonsmoking patients did we find an increased expression level of TP63 and EGFR genes in tumor tissue compared to peritumor tissue." (PMID 38540309, 2024). "Notably, ΔNp63, the major TP63 isoform with oncogenic functions, is more highly expressed in primary LUSC tumor samples than the full-length Tap63 (linear model p-value < 0.001)." (PMID 37150829, 2023). "The knockdown of TP63 in cells of MMTV-ERBB2 tumor-derived mammospheres, which dominantly express the ΔNp63 isoform but not the TA isoform, decreases mammosphere formation in vitro and in tumor formation in vivo." (PMID 36292946, 2022). "Other signature genes (TP63, CERS3, CSTA, CLCA2, DSC3 and DSG3) upregulated in C1 tumours are also markers of the squamous-like subtype, while further columnar-like marker genes (MUC5B and RGL3) are upregulated in C2 tumours." (PMID 36207323, 2022). "TP63 had a strong correlation with SLUG expression in the bioinformatics analyses, which might influence EMT, CIP and/or apoptotic regulation of the tumor cells, that urges further investigations." (PMID 35201505, 2022). "Furthermore, we identified potential molecular targets based on our expression data in NE-low and immune-oasis tumor subsets, including CD70, ANXA1, ITGB6, TP63, IFI27, YBX3 and CXCR2." (PMID 34200100, 2021). "ALOXB15, TP63 and PLIN4 were obviously downregulated in tumor samples compared to normal ones." (PMID 34715817, 2021). "Furthermore, the gene expression alterations in tumour tissues were consistent with the in vitro observations: upregulation of PTGS2 and CYP2E1 and down-regulation of TP63 and KRT5." (PMID 33359448, 2021). "In addition, we validated (i) the co-regulatory feedback loop between SREBF1/TP63/KLF5, and (ii) canonical target genes of SREBF1 in fatty-acid metabolism (e.g., ACLY, FASN, and SCD) in xenograft tumor samples." (PMID 34272396, 2021).
tumor (continued). "Flores and colleagues observed the development of spontaneous tumours in TP63+/− mice, while Keyes and Mills did not obtain the same results, this difference being probably due to the failure to create p63 isoform-specific knockout mice." (PMID 31789342, 2019). "Notably, Tp63 is required for the development of spontaneous SCC observed in ASPP2−/+ BALB/c heterozygous mice, implicating p63 as a critical mediator of ASPP2 tumour‐suppressive function in SCC." (PMID 30845357, 2019). "Moreover, tumor sphere cells expressed higher CD49f and lower ASMA than parental cells, while both parental cells and tumor sphere cells were EpCAM+TP63-." (PMID 31196164, 2019). "TP63 has previously been shown to be expressed in the tumour cells in human ACP, but APCDD1L and BCL11B have not been implicated in ACP." (PMID 29541918, 2018). "Although not predicted from the tumour analyses, knockdown of Δ133TP53 also resulted in reduced expression of 7/8 genes as was TP63." (PMID 30018742, 2018). "In addition, miR-21-5p was controlled by one gene called miR-21 and in previous studies, miR-21 has been proved to be capable of targeting many tumor suppressors such as PTEN, RECK, BTG2 and TP63." (PMID 30134821, 2018). "It has been previously demonstrated that the TP63/TP53L, ERG, GRHL1/Get-, HNF1A/TCF-1, SPI1/PU.1, WT1 and GLIS2, FOXM1 and FOXP3 transcription factor networks, which are mediated by HNF4A, can regulate the expression of Trop2 in tumor tissues." (PMID 25779928, 2015). "Furthermore, TP63+ SLC7A5+ HNSCC subpopulation may resist phagocytosis by macrophages through the CD24-SIGLEC10 axis, promoting tumor escape." (PMID 39234254, 2024). "We next investigated the regulatory mechanism of TP63 on SREBF1 transcription in SCC, focusing on ESCC model because compared with HNSC and LUSC, ESCC not only showed the highest expression of SREBF1, but also had the highest tumor/normal ratio (that is, the greatest upregulation in tumors)." (PMID 34272396, 2021). "TP63 was highly expressed in normal tissues but not detected in tumor tissues." (PMID 32649310, 2020).
tumor (continued). "As compared with ALDHlowCD44high non-stem tumor cells, increased enrichments of both p65 and BRD4 on SEs in both TP63 and MET were observed in ALDHhighCD44high CSCs." (PMID 34172737, 2021). "JQ1 had little effect on TP63 and MET expression in ALDHlowCD44high non-stem tumor cells." (PMID 34172737, 2021). "Notably, canonical breast cell differentiation genes and molecular markers (KRT8, KRT18, KRT14, TP63, ERBB2, ESR1, PGR) were not differentially expressed, suggesting the cells maintain their differentiation state and tumor subtype." (PMID 34741115, 2021). "The GU‐Uro tumours differed from Uro tumours by increased proliferation, immune and extracellular matrix (ECM) mRNA signatures, but protein expression levels of the canonical Uro genes FGFR3, CCND1 and TP63 were not different in the Uro versus GU‐Uro groups of tumours." (PMID 28195647, 2017).
cancer (175 papers, 2001 to 2026). A tumor composed of atypical neoplastic, often pleomorphic cells that invade other tissues. "KRT5 and TP63 are known epithelial and basal markers, and their overexpression has been implicated in pathways and lineages that drive carcinoma progression." (PMID 41362277, 2026). "TP63 is rarely mutated in cancer but is often overexpressed and/or amplified in specific cancerous settings." (PMID 40498028, 2025). "Similar to the case in CLL, miRNA-mediated downregulation of TP63 is associated with cancer progression in PC." (PMID 39791744, 2025). "Consistent with the oncogenic role of TP63 in SCC, genes positively correlated with TP63 expression were enriched in cancer-promoting hallmark pathways, including E2F targets, G2M checkpoint, MYC targets and mTOR signaling pathways." (PMID 38509096, 2024). "From the top down- and up-regulated DEG, four genes (ADAMTS1, FGF1, G0S2 and TP63) were also closely associated with cancer pathways according to the literature." (PMID 35840561, 2022). "Increased self-renewal of cancer cells is caused by commonly found copy number amplifications of the transcription factors (TFs) TP63 and SOX2, which promote survival and inhibit squamous differentiation." (PMID 35159370, 2022). "TP63 mutations, which are present in the majority of cancers, are associated with poorer clinical outcomes in SKCM, which is consistent with our findings." (PMID 36685905, 2022). "This study will serve as a benchmark for further validation of the association of TP63 SNPs with cancers." (PMID 34827731, 2021). "Genome-wide association studies (GWAS) have identified SNPs located in the tumor protein 63 (TP63) locus to be associated with the genetic susceptibility of cancers." (PMID 34827731, 2021). "nsSNPs of the TP63 gene were found to be associated with different types of disorders along with cancers." (PMID 34827731, 2021). "The poor survival samples also over-expressed CTNNB1 and SOX4 and under-expressed PIK3R1 and TP63, all of which have been linked to tumorigenesis in other cancers." (PMID 29484115, 2018). "Stem-like cell properties are important factors for cancer progression and metastasis, and TP63 has been implicated in the stemness properties of stratified epithelia and cancers." (PMID 28423539, 2017). "Altered expression of the TP63 is linked to cancer progression and metastasis." (PMID 39791744, 2025). "TP63 is rarely mutated in human cancers but its expression and activity are often increased." (PMID 37848625, 2023). "As TP73 and TP63 are rarely mutated in cancers the analysis of the methylation status of P1 and P2 might contribute to our understanding of the resistance disease." (PMID 35806218, 2022). "From our results, it can be predicted that nsSNPs create deleterious changes in TP63 structure and function and may potentially cause diseases such as cancers." (PMID 34827731, 2021). "Several genome-wide association studies (GWAS) and case-control studies have shown the association of single nucleotide polymorphisms (SNPs) in the human TP63 locus with various cancers, i.e., lung cancer, head and neck cancer, colon cancer, urinary bladder cancer, and other diseases." (PMID 34827731, 2021).
cancer (continued). "Therefore, the association of this functional variant rs17506395 of the TP63 gene in young Cameroonian women would partially justify the aggressiveness of cancer among young black women in sub-Saharan Africa." (PMID 32856845, 2020). "In contrast to the cancer, mutations within the TP63 gene are common in epidermal dysplasia." (PMID 31744230, 2019). "Like STAT3, TP63 is rarely mutated in human cancer, but p63 activity is often increased." (PMID 29588647, 2018). "TP63 is a powerful diagnostic discriminant, and a cancer prognostic and predictive factor." (PMID 30473748, 2018). "Moreover, the EMT-inhibiting EHF and TP63 were down-regulated and the cancer invasion-associated EPSTI1 was up-regulated implying that proliferation of mesenchymal elements and may be important in the epithelial plasticity and cancer progression." (PMID 25706888, 2015). "The volcano plot further confirmed the importance of these genes by pinpointing significantly upregulated and downregulated genes, such as TP63, NTRK2, and CLCA2, which are strongly associated with cancer." (PMID 40370696, 2025). "FZD7/β-catenin/TP63 Axis: Specifically activated in cancer cells, conferring resistance to ferroptosis by regulating genes involved in glutathione (GSH) metabolism." (PMID 41479924, 2025). "In a more recent study looking at specific isoforms of TP63 and its correlation to the survival of cancer patients, the authors performed an RNA-seq of patient samples and correlated gene expression to patient outcome." (PMID 39791744, 2025). "Due to this complexity, it is essential to thoroughly examine the role of TP63 isoforms and miR-205 in each specific type of cancer." (PMID 40181048, 2025). "Of the 14 signature genes, NAIP and TP63 were considered marker genes for mononuclear phagocytes and ureteric bud-like cancer cells respectively in the sample of favorable histology." (PMID 38678251, 2024). "In contrast, tumors with high TP63 expression had only a few scattered CD8+ T cells at the edge of cancer lesions." (PMID 38509096, 2024). "The findings highlight TDP‐43 as a viable therapeutic target for ESCC and uncover a hitherto unrecognized TDP‐43/TP63 circuit in cancer." (PMID 39023169, 2024). "This study underscores the potential of TP63 as a biomarker for detecting cancer recurrence and suggests its role in guiding future treatment options." (PMID 38791062, 2024). "The study highlights TDP‐43 as a viable therapeutic target and uncovers an unrecognized TDP‐43/TP63 positive feedback pathway in cancers." (PMID 39023169, 2024). "Among 33 cancer types analyzed by Pan TCGA, the TP63 and HRAS genes are significantly overexpressed in human head and neck and lung SCCs compared to normal tissues." (PMID 37638000, 2023). "Because of their adjacent chromosomal localization (3q), SOX2 and TP63 are frequently co-amplified in cancer." (PMID 37046726, 2023). "Whereas the association with HERVH-CALB1 expression extended to other cancer types for some transcription factors (SOX2, SOX21), for others (TP63, FOXE1), it was specific to LUSC." (PMID 37192000, 2023). "An in-depth study of the relationship between miR-944 and TP63 and ΔNp63 can broaden the understanding of the molecular mechanism of miR-944 in cancer." (PMID 36077769, 2022). "Clearly, further experiments using the improved isoform-specific reagents now available will be required to determine the expression patterns of TP63 isoforms in this cancer type." (PMID 35912167, 2022).